WDR43 (WD repeat domain 43)
Diseases named in the same sentence as WDR43 in open-access papers:
WDR43 is named in the same sentence as 50 diseases in open-access papers, as found by Europe PMC text mining. Sharing a sentence is not in itself a finding about the gene and the disease. The quoted sentences say what the papers report.
breast carcinoma (2 papers, 2016 to 2024). "Thus, WDR43 and TRMT61B may be regulated by interactions of enhancers in WDR43 with the core WDR43 and TRMT61B promoters and may jointly influence breast cancer risk in this region." (PMID 27117709, 2016).
cervical cancer (2 papers, 2021 to 2024). A primary or metastatic malignant neoplasm involving the cervix. "The expression level of CTU1, RBM38, WDR43 varies with different pathology of cervical cancer." (PMID 34863153, 2021). "It is displayed in kaplan–Meier curves that higher expression level of EEF1D, CTU1, EIF3C, WDR43, NUFIP1, ZC3HAV1L and PRPF40B indicated a lower overall survival of cervical cancer patients." (PMID 34863153, 2021).
colorectal cancer (2 papers, 2021 to 2023). A primary or metastatic malignant neoplasm that affects the colon or rectum. "In addition, WDR43 has been implicated in the development of human estrogen receptor-negative breast cancer and identified as a possible therapeutic target for colorectal cancer." (PMID 37122373, 2023). "WDR43 may serve as a valuable biomarker and provide new options for the diagnosis and treatment of colorectal cancer." (PMID 34372874, 2021).
osteoarthritis (2 papers, 2022 to 2023). A noninflammatory degenerative joint disease occurring chiefly in older persons, characterized by degeneration of the articular cartilage, hypertrophy of bone at the margins and changes in the synovial membrane. "Recent studies have suggested that the WD repeat protein family member, WDR43, may play a role in the development of Parkinson’s disease (PD) and serve as a potential diagnostic biomarker and therapeutic target for PD with comorbid osteoarthritis." (PMID 37122373, 2023).
acute myeloid leukemia (1 paper, 2024). Acute myeloid leukemia (AML) is a group of neoplasms arising from precursor cells committed to the myeloid cell-line differentiation. "Stromal scores in TGCT (r = −0.5, P = 2.6e-11), STAD (r = −0.4, P < 2.2e-16), LUSC (r = −0.34, P < 2.2e-16), acute myeloid leukemia (r = −0.35, P = 1.1e-05), skin cutaneous melanoma (r = −0.31, P = 7.2e-05) were negatively correlated with WDR43 expression." (PMID 39093744, 2024). "In acute myeloid leukemia (r = −0.48, P = 4.3e-10), ESCA (r = −0.38, P = 6.4e-07), LUSC (r = −0.36, P < 2.2e-16), HNSC (r = −0.32, P = 2.4e-16), significant negative correlations among WDR43 expression and ImmuneScore were observed." (PMID 39093744, 2024).
adrenocortical carcinoma (1 paper, 2024). "Furthermore, the utilization of GEPIA2 datasets revealed a significant connection between WDR43 expression levels and various pathological stages across multiple cancer forms, such as adrenocortical carcinoma (ACC), LIHC, LUAD, KIRP, PAAD, and uterine carcinosarcoma." (PMID 39093744, 2024).
aneurysm (1 paper, 2023). Bulging or ballooning in an area of an artery secondary to arterial wall weakening. "The study found upregulated genes (including WDR43 and THBS1) and one downregulated gene associated with aneurysm rupture." (PMID 37122373, 2023). "While our study identified 11 upregulated genes, including WDR43 and THBS1, and one downregulated gene associated with aneurysm rupture, we acknowledge the limitations of not conducting relevant experiments on miRNA." (PMID 37122373, 2023).
aortic aneurysm (1 paper, 2023). A ruptured aneurysm located in the wall of the proximal portion of the descending aorta proceeding from the arch of the aorta. "DEmiRNAs associated with ruptured aortic aneurysm were identified, of which two could bind to THBS1 and WDR43." (PMID 37122373, 2023).
breast invasive carcinoma (1 paper, 2024). "The protein expression of WDR43 exhibited a statistically significant increase in UCEC, COAD, LUAD, LGG, HNSC, breast invasive carcinoma, renal papillary cell carcinoma (KIRP), and tumor tissue compared to para-cancerous tissue, based on online data obtained from CPTAC datasets." (PMID 39093744, 2024).
colon cancer (1 paper, 2022). "Our findings indicated that DEDD2, GTF2H5, SNRPA1, BICD1, CELF1, and CLK3 were prognostic risk factors for colon cancer, while ADAD1, CMTR1, HNRNPUL1, FTSJ3, WDR43, THUMPD3, SNRPF were prognostic protective factors." (PMID 36212157, 2022).
dementia (1 paper, 2023). Loss of intellectual abilities interfering with an individual's social and occupational functions. "Our findings propose that Cromolyn may forestall dementia by targeting and regulating WDR43 in elderly patients with CV and neuronal inflammatory damage caused by SAH." (PMID 37122373, 2023). "The findings suggest that WDR43 and THBS1 are potential targets for preventing and treating CV-induced dementia in the elderly." (PMID 37122373, 2023).
diffuse large B-cell lymphoma (1 paper, 2024). "Our findings revealed that compared with the normal controls, WDR43 expression exhibited a significant increase within tumors, including COAD, GBM, STAD, ESCA, pancreatic adenocarcinoma (PAAD), lower grade glioma (LGG), diffuse large B-cell lymphoma (DLBC), thymoma, LUSC, and READ (P < .05)." (PMID 39093744, 2024).
endocervical carcinoma (1 paper, 2024). A carcinoma that arises from epithelial cells of the endocervix. "The KM analysis outcomes exhibited that the overexpression of WDR43 was correlated with shorter OS in PAAD, UCEC, LUAD, HNSC, sarcoma (SARC), LIHC, KIRP, and cervical and endocervical cancer (CESC)." (PMID 39093744, 2024).
endometrial cancer (1 paper, 2024). Primary or metastatic malignant neoplasm involving the endometrium (mucous membrane that lines the endometrial cavity). "The findings showed that WDR43 exhibited the highest alteration frequencies in endometrial cancer (5.46%), with “mutation” (3.58%) and “amplification” (1.88%) being the 2 most common alteration types." (PMID 39093744, 2024).
esophageal squamous cell carcinoma (1 paper, 2024). Esophageal squamous cell carcinoma (ESCC) is a type of esophageal carcinoma (EC) that can affect any part of the esophagus, but is usually located in the upper or middle third. "In contrast, the upregulation of WDR43 in READ, STAD, esophageal squamous cell carcinoma, and KIRC correlated with longer OS." (PMID 39093744, 2024).
head and neck squamous cell carcinoma (1 paper, 2024). A squamous cell carcinoma that arises from any of the following anatomic sites: lip and oral cavity, nasal cavity, paranasal sinuses, pharynx, larynx, and salivary glands. "Upregulation of WDR43 was associated with unfavorable prognosis, including overall survival in various types of cancer such as LIHC, uterine corpus endometrial cancer, head and neck squamous cell carcinoma, and pancreatic adenocarcinoma." (PMID 39093744, 2024).
jaw cysts (1 paper, 2026). "The identified 6 proteins, namely CD79A, CD5, KRR1, UTP20, AATF, and WDR43 - may be closely associated with the pathogenesis of jaw cysts." (PMID 42175431, 2026).
lung carcinoma (1 paper, 2023). "Intriguingly, several bioinformatics analysis identified WDR43 as a crucial oncogene contributing to the development of colorectal/lung cancer via promoting the migration and proliferation of cancer cells through GEO and The Cancer Genome Atlas (TCGA) database." (PMID 38110868, 2023).
Lynch syndrome (1 paper, 2026). An autosomal dominant hereditary neoplastic syndrome characterized by the development of colorectal carcinoma and a high risk of developing endometrial carcinoma, gastric carcinoma, ovarian carcinoma, renal pelvis carcinoma, and small intestinal carcinoma. "In addition, the Lynch syndrome samples showed substantial sex-based differences in immune and inflammatory pathways, for example, downregulation of ZG16, DIS3, and WDR43." (PMID 41727057, 2026).
mesothelioma (1 paper, 2024). A usually malignant and aggressive neoplasm of the mesothelium which is often associated with exposure to asbestos. "Furthermore, in GEPIA2, overexpression of WDR43 was correlated with unfavorable OS in ACC, CESC, KICH, KIRP, LIHC, and mesothelioma (MESO) but correlated with positive OS in KIRC." (PMID 39093744, 2024).
Sepsis (1 paper, 2024). Sepsis is defined as life-threatening organ dysfunction caused by a dysregulated host response to infection. "Therefore, low expression of WDR43 in SIM may play a role in attenuating the Rho pathway and subsequently protecting the vascular endothelium and vascular tone in sepsis, thereby slowing down skeletal muscle injury in SIM." (PMID 39438952, 2024).
subarachnoid hemorrhage (1 paper, 2023). A serious neurological disorder characterized by intracranial hemorrhage into the subarachnoid space. "Of note, cromolyn has the potential to block the hsa-miR-877-3p/WDR43 pathway and may be a promising candidate for preventing CV events after subarachnoid hemorrhage." (PMID 37122373, 2023).
thymoma (1 paper, 2024). A neoplasm arising from the epithelial cells of the thymus. "Additionally, we discovered that WDR43 expression demonstrated a robust positive association with tumor-related fibroblast infiltration in LIHC, KICH, thymoma, HNSC, HNSC-HPV+, ACC, LUAD, and GBM." (PMID 39093744, 2024).
thyroid carcinoma (1 paper, 2024). "Intriguingly, WDR43 differential expression has been discovered to exhibit significant reduction within tissues of thyroid carcinoma (THCA) and kidney chromophobe (KICH) as compared to control tissues." (PMID 39093744, 2024).
Treacher-Collins syndrome (1 paper, 2014). A congenital disorder of craniofacial development characterized by bilateral symmetrical oto-mandibular dysplasia without abnormalities of the extremities, and associated with several head and neck defects. "Together, our findings provide new insight into roles for Wdr43 in development, ribosome biogenesis, and also ribosomopathy-induced craniofacial phenotypes including Treacher-Collins Syndrome." (PMID 24497835, 2014).
viral infection (1 paper, 2021). "After 24 and 48 h of viral infection, the migrating and invasive cells were counted, and it was found that WDR43 knockdown inhibited the migration and invasion of CRC cells." (PMID 34372874, 2021).
cancer (8 papers, 2021 to 2024). A tumor composed of atypical neoplastic, often pleomorphic cells that invade other tissues. "We conducted a thorough investigation of the clinical features, phases of tumor development, immune infiltration, gene mutation, and functional enrichment analysis of WDR43 in various types of cancer." (PMID 39093744, 2024). "We analyzed the association between the expression of WDR43 and the ImmuneScore and StromalScore within pan-cancer." (PMID 39093744, 2024). "WDR43 expression demonstrated better association with the 5 different MMR genes in pan-cancer, except for gene EPCAM in LGG." (PMID 39093744, 2024). "An example is that the expression level of WDR43 demonstrated a favorable association with T helper cells, Tcm, and Th2 cells while displaying a poor association with NK cells, NK CD56bright cells, and pDC in pan cancers." (PMID 39093744, 2024). "Therefore, the diagnostic and predictive potential of WDR43 in various cancers requires further validation, especially in LIHC in a specific clinical cohort." (PMID 39093744, 2024). "The predominant genetic modification observed in cancers affecting WDR43 is the modifications resulting from missense mutation, with the D474N mutation situated at the Utp12 domain associated with the greatest quantity of individuals comprising the WDR43 mutation." (PMID 39093744, 2024). "Furthermore, we determined whether there was an association between the genetic modification of WDR43 and prediction for all forms of TCGA cancer." (PMID 39093744, 2024). "We also determined the connection between WDR43 expression and immune checkpoint within 33 cancer forms." (PMID 39093744, 2024). "WDR43 different expression levels in various cancers were positively correlated with chemokines, including C-X-C motif chemokine ligand (CXCL) 9, CXCL10, and CXCL11." (PMID 39093744, 2024). "In this study, we analyzed the expression and prognostic significance of WDR43 in pan-cancer using the Cancer Genome Atlas, the Genotype-Tissue Expression, and the Human Protein Atlas." (PMID 39093744, 2024). "This study utilized bioinformatics tools to investigate the relationship between WDR43 expression levels and cancer prognosis and the connection between WDR43 expression and tumor immunity by analyzing WDR43 expression levels in multiple cancer types." (PMID 39093744, 2024). "These outcomes indicate that WDR43 expression affects the prediction of various forms of cancers, such as OS, DSS, PFI, and RFS." (PMID 39093744, 2024). "The present investigation provided supporting evidence that WDR43 exhibited differential expression patterns across multiple forms of cancer and that its anomalous expression was connected to the advancement of tumors." (PMID 39093744, 2024). "Recent findings have provided novel perspectives on implementing personalized cancer immunotherapy by revealing WDR43’s involvement in tumorigenesis and progression." (PMID 39093744, 2024). "Our results showed that cromolyn formed the best docking complex with WDR43, indicating a potential therapeutic target for the treatment of cancer." (PMID 37122373, 2023). "The expression level of EEF1D, RBM38 and WDR43 ascended with the progression of cancer pathology grade." (PMID 34863153, 2021). "The immunohistochemical score (% of positive cells × staining intensity) showed that the expression level of WDR43 in CRC tumor tissue was higher compared with that cancer-adjacent normal tissues." (PMID 34372874, 2021). "Conducting prospective research that sheds light on the connection between tumor immunity and the expression of WDR43 may yield valuable findings and facilitate the advancement of immunotherapeutic approaches that target WDR43 for cancer management." (PMID 39093744, 2024). "Additionally, based on TCGA data, Cox proportional hazards model analysis was conducted to assess the predictive significance of the WDR43 in various forms of cancer." (PMID 39093744, 2024).
cancer (continued). "For investigating the connection among clinical outcomes and WDR43 expression in pan-cancer, a KM survival analysis has been conducted to examine the predictive significance of WDR43, such as progression-free interval (PFI), disease-specific survival (DSS), OS, and recurrence-free survival (RFS)." (PMID 39093744, 2024). "Additionally, cancer cells with higher WDR43 expression were more resistant to chemotherapy-mediated cell death and therefore the overexpression of WDR43 was related to the poor prognosis of CRC patients." (PMID 38098990, 2023). "However, little is known about the role of WDR43 in cancer prognosis and immune modulation." (PMID 39093744, 2024). "Additionally, GSEA revealed that increased WDR43 expression in pan-cancer may contribute to the immune-related functions, including immune regulation, immune responses, and signaling pathways." (PMID 39093744, 2024). "Following a search of the TCGA database, the expression of WDR43 was found to be increased in CRC, as compared to that in cancer-adjacent normal colon tissue." (PMID 34372874, 2021). "Based on the correlation between WDR protein and cancer, CRC-related genes were screened out by genome-wide gene expression profiling, and WDR43 was selected to explore its impact on tumor biological functions." (PMID 34372874, 2021). "Additionally, we analyzed the top 100 genes coexpressed with SELENOI across 33 cancer types using GEPIA2.0, and identified PUM2, STRN, WDR43, PRPF40A, and SPAST as highly correlated with SELENOI." (PMID 39669976, 2024). "No statistical significance variation was found within the prognosis observed among the groups of individuals with modified and unmodified WDR43 for the other TCGA cancers (data not shown)." (PMID 39093744, 2024). "However, the expression of WDR43 in liver hepatocellular carcinoma (LIHC) and its precise function in pan-cancer are still unknown." (PMID 39093744, 2024).
tumor (3 papers, 2021 to 2024). "The study involved gene co-expression assay to investigate the association among WDR43 differential expression and immune-associated genes across 33 distinct tumor types." (PMID 39093744, 2024). "First, we utilized 3 datasets to investigate the association between the differential expression of WDR43 and OS within 33 distinct tumor types." (PMID 39093744, 2024). "The present investigation findings demonstrate that WDR43 expression is strongly linked to tumor cell immune infiltration, influences individual prognosis, and suggests potential immunosuppressive drug targets." (PMID 39093744, 2024). "Additionally, we investigated the correlation between WDR43 and clinical characteristics, gene alterations, tumor mutation burden, microsatellite instability, mismatch repair, tumor microenvironment, immune infiltrating cells, and immune-related genes using bioinformatics methods." (PMID 39093744, 2024). "The results revealed that WDR43 is a promising biomarker correlated with tumor detection and response to immunotherapeutic agents." (PMID 39093744, 2024). "As compared with the control group, the tumor volume and weight of mice in the WDR43 knockdown group was reduced, while the tumor volume and weight of mice with both WDR43 knockdown and VIM overexpression were significantly recovered." (PMID 34372874, 2021). "Our results imply that WDR43 regulates tumor immunity and inflammatory response." (PMID 39093744, 2024). "The current investigation findings indicate that WDR43 may modulate tumor growth via modulating DNA mismatch repair." (PMID 39093744, 2024). "Therefore, a low WDR43 expression decreases the growth of tumor in vivo, which was accord with our research in vitro and clinical discoveries." (PMID 34372874, 2021). "In addition, the expression level of EEF1D, RBM38 and WDR43 ascended with higher tumor pathology grade (p-value = 0.019, 0.020, 0.034)." (PMID 34863153, 2021).
neurodegenerative disease (1 paper, 2023). A disorder of the central nervous system characterized by gradual and progressive loss of neural tissue and neurologic function. "Although we speculate that WDR43 may be indirectly involved in the development of CV and neurodegeneration following SAH, further research is needed to elucidate its precise mechanisms and potential as a diagnostic biomarker and therapeutic target for these neurodegenerative diseases." (PMID 37122373, 2023).
WDR43 also shares sentences with these, for which no sentence is quoted: cholangiocarcinoma (1 paper); colon adenocarcinoma (1); esophageal carcinoma (1); glioblastoma (1); glioma (1); infection (1); lung adenocarcinoma (1); lung squamous cell carcinoma (1); melanoma (1); ovarian serous cystadenocarcinoma (1); pancreatic adenocarcinoma (1); paraganglioma (1); Parkinson disease (1); pheochromocytoma (1); rectum adenocarcinoma (1); renal papillary cell carcinoma (1); sarcoma (1); skin cutaneous melanoma (1); stomach adenocarcinoma (1); uterine carcinosarcoma (1); uterine corpus endometrial carcinoma (1).